SNORD50B (small nucleolar RNA, C/D box 50B)
Synonyms: U50B; U50'
Gene: Small nucleolar RNA gene on chromosome 6 (85,677,589 to 85,677,658, reverse strand). Ensembl gene ENSG00000275072.
Gene Ontology:
Biological process: RNA processing
Cellular component: nucleolus
Homologues: Orthologues: chimpanzee SNORD50B (100% identical), macaque SNORD50B (99% identical), guinea pig SNORD50B (93% identical), pig SNORD50B (93% identical), rabbit SNORD50B (87% identical).
Diseases named in the same sentence as SNORD50B in open-access papers:
SNORD50B is named in the same sentence as 3 diseases in open-access papers, as found by Europe PMC text mining. Sharing a sentence is not in itself a finding about the gene and the disease. The quoted sentences say what the papers report.
tumor (3 papers, 2016 to 2023). "SNORD126 is reported to be up-regulated and activates the PI3K-AKT pathway to promote tumor growth, and SNORD50A and SNORD50B function as tumor suppressors via repressing the activity of K-Ras pathway." (PMID 37006268, 2023).
SNORD50B also shares sentences with these, for which no sentence is quoted: breast carcinoma (3 papers); colon cancer (1).